SLC30A7 (solute carrier family 30 member 7)
Description:
Zinc ion transporter mediating zinc entry from the cytosol into the lumen of organelles along the secretory pathway. By contributing to zinc ion homeostasis within the early secretory pathway, regulates the activation and folding of enzymes like alkaline phosphatases.
Synonyms: ZnT-7; ZNT7; ZNTL2; ZHS
Tractability: Antibody: UniProt predicts a signal peptide or a membrane-spanning region. PROTAC: ubiquitination databases record sites on it; its protein half-life has been measured.
Target class: Transporter
Gene: Protein-coding gene on chromosome 1 (100,896,061 to 100,996,260, forward strand). Ensembl gene ENSG00000162695.
Subcellular location: Golgi apparatus membrane; Cytoplasmic vesicle; Golgi apparatus, trans-Golgi network; Sarcoplasmic reticulum; Mitochondrion; Cytoplasm
Subcellular location (Human Protein Atlas): Golgi apparatus
Gene Ontology:
Molecular function: identical protein binding; zinc ion transmembrane transporter activity; monoatomic cation transmembrane transporter activity
Biological process: zinc ion import into Golgi lumen; intracellular zinc ion homeostasis; monoatomic cation transport; transmembrane transport; zinc ion transport
Cellular component: cytoplasm; Golgi apparatus; Golgi cis cisterna membrane; Golgi membrane; transmembrane transporter complex; vesicle; cytoplasmic vesicle; mitochondrion; sarcoplasmic reticulum; sarcoplasmic reticulum membrane; vesicle membrane; membrane; perinuclear region of cytoplasm
Genetic constraint (gnomAD): Loss-of-function variants: 23 observed, 29.19 expected, observed/expected ratio (o/e) 0.79, 90% interval 0.57 to 1.12. The upper end of that interval is the gene's LOEUF score, 1.12, which puts it in group 4 of 6, group 1 being the genes least tolerant of losing a copy. Missense variants: 367 observed, 362.43 expected, observed/expected ratio (o/e) 1.01, 90% interval 0.93 to 1.1. Synonymous variants: 114 observed, 125.56 expected, observed/expected ratio (o/e) 0.91, 90% interval 0.78 to 1.06.
Homologues: Orthologues: macaque SLC30A7 (99% identical), chimpanzee SLC30A7 (99% identical), dog SLC30A7 (98% identical), pig SLC30A7 (97% identical), rabbit SLC30A7 (97% identical), mouse Slc30a7 (96% identical), guinea pig SLC30A7 (93% identical), zebrafish slc30a7 (79% identical), tropical clawed frog slc30a7 (76% identical), rat Slc30a7 (61% identical), Drosophila melanogaster ZnT86D (60% identical). Paralogues in human: SLC30A5 (43% identical), SLC30A10 (25% identical), SLC30A1 (24% identical), SLC30A6 (19% identical), SLC30A4 (18% identical), SLC30A3 (18% identical), SLC30A2 (16% identical), SLC30A8 (16% identical).
Diseases named in the same sentence as SLC30A7 in open-access papers:
SLC30A7 is named in the same sentence as 35 diseases in open-access papers, as found by Europe PMC text mining. Sharing a sentence is not in itself a finding about the gene and the disease. The quoted sentences say what the papers report.
prostate tumors (5 papers, 2020 to 2024). "who showed a null-mutation of SLC30A7 caused acceleration of prostate tumour formation." (PMID 36937454, 2023). "Whilst a null-mutation of SLC30A7 in the Transgenic Adenocarcinoma of Mouse Prostate (TRAMP) mouse model of PCa accelerated prostate tumour formation, the role of SLC30A7 in CRPC has not been extensively studied." (PMID 36937454, 2023).
amyotrophic lateral sclerosis (1 paper, 2021). Amyotrophic lateral sclerosis (ALS) is a neurodegenerative disease characterized by progressive muscular paralysis reflecting degeneration of motor neurons in the primary motor cortex, corticospinal tracts, brainstem and spinal cord. "Moreover, we identified Wald ratio effects between four genes (IQCB, TTC34, MPV17L2 and SLC30A7) and multiple sclerosis risk, and effects between two genes (SCFD1, G2E3) and amyotrophic lateral sclerosis risk." (PMID 33417599, 2021).
cervical cancer (1 paper, 2022). A primary or metastatic malignant neoplasm involving the cervix. "Data in the UALCAN tool revealed that mRNA expressions of SLC30A1, SLC30A7 and SLC30A10 were significantly higher in cervical cancer tissues, while SLC30A2 and SLC30A8 mRNA levels were decreased compared to normal tissues." (PMID 35154468, 2022). "For metastases, we found that SLC30A1, SLC30A7 and SLC30A10 expression were positively correlated with lymph node metastasis or distant metastasis in cervical carcinoma." (PMID 35154468, 2022). "Besides, we found that SLC30A1, SLC30A7 and SLC30A10 expression was positively correlated with lymph node metastasis or distant metastasis in cervical carcinoma." (PMID 35154468, 2022). "For tumor stages, SLC30A1, SLC30A7 and SLC30A10 groups significantly varied, whereas SLC30A2, SLC30A3, SLC30A4, SLC30A5, SLC30A6, SLC30A8 and SLC30A9 did not significantly differ in cervical carcinoma." (PMID 35154468, 2022).
diabetic cardiomyopathy (1 paper, 2023). Diabetic cardiomyopathy is a disorder of the heart muscle in people with diabetes. "SLC30A7 is involved in the regulation of insulin secretion and in the regulation of diabetic cardiomyopathy progression by influencing muco-mitochondrial coupling in hyperglycemic cardiomyocytes." (PMID 36674633, 2023).
gastric adenocarcinoma (1 paper, 2023). "In addition, we found that the expression levels of SLC30A1, SLC30A5, SLC30A6 and SLC30A7 were significantly elevated, while the expression level of SLC30A4 was significantly decreased in gastric adenocarcinoma tissues compared with both normal gastric tissues and matched normal gastric tissues." (PMID 37524874, 2023).
glioma (1 paper, 2024). A benign or malignant brain and spinal cord tumor that arises from glial cells (astrocytes, oligodendrocytes, ependymal cells). "CCK-8 and wound-healing and Transwell assay verified that silencing SLC30A7 significantly attenuated the proliferation, migration, and invasion of glioma cells." (PMID 38393693, 2024).
Joubert syndrome (1 paper, 2024). Joubert syndrome (JS) is characterized by congenital malformation of the brainstem and agenesis or hypoplasia of the cerebellar vermis leading to an abnormal respiratory pattern, nystagmus, hypotonia, ataxia, and delay in achieving motor milestones. "Although no SLC30A7 variants have yet been shown to cause human phenotypes or diseases, SLC30A7 is a candidate gene associated with Joubert syndrome." (PMID 38474291, 2024). "Recently, a de novo heterozygous variant of SLC30A7, His164Ser, was found in Joubert syndrome patients." (PMID 38474291, 2024).
tumor (9 papers, 2016 to 2024). "Intracranial orthotopic xenotransplantation models were constructed to verify that silencing SLC30A7 significantly decreased transplant tumour size." (PMID 38393693, 2024). "SLC30A7 may be involved in tumour initiation and progression." (PMID 38393693, 2024). "For tumor stages, SLC30A1, SLC30A7 and SLC30A10 groups significantly varied." (PMID 35154468, 2022).
cancer (5 papers, 2019 to 2024). A tumor composed of atypical neoplastic, often pleomorphic cells that invade other tissues. "As AR-V7 decreases the activity of the protein encoded by SLC30A7 that transports zinc, this could cause more DNA damage and impair DNA repair and thus allows new mutations in cancer, causing disease progression." (PMID 36937454, 2023).
SLC30A7 also shares sentences with these, for which no sentence is quoted: Zinc deficiency (6 papers); prostate carcinoma (4); Insulin resistance (3); Adenocarcinoma of (2); bladder (2); colorectal cancer (2); diabetes (2); Hyperglycemia (2); Alzheimer disease (1); bacterial infection (1); diabetic retinopathy (1); esophageal squamous cell carcinoma (1); gastric cancer (1); Glucose intolerance (1); hepatocellular carcinoma (1); infection (1); insulinoma (1); leukemia (1); lymph node metastasis (1); lymphoma (1); melanoma (1); metabolic syndrome (1); multiple sclerosis (1); Prostate (1); prostate adenocarcinoma (1); unipolar depression (1).